FGL1 (fibrinogen like 1)
Diseases named in the same sentence as FGL1 in open-access papers (continued):
Sharing a sentence is not in itself a finding about the gene and the disease.
lung adenocarcinoma (14 papers, 2019 to 2025). A carcinoma that arises from the lung and is characterized by the presence of malignant glandular epithelial cells. "Silencing FGL1 was found to be a novel approach for the treatment of LKB1 mutated lung adenocarcinoma by inducing EMT and angiogenesis." (PMID 34975333, 2022). "In LKB1 mutant lung adenocarcinoma, loss of FGL1 was found to promote angiogenesis and epithelial-mesenchymal transition, leading to poor prognosis." (PMID 35776395, 2022). "Therefore, the role of FGL1 in different tumors varies, acting as a tumor suppressor gene in lung adenocarcinoma with LKB1 mutation." (PMID 41024301, 2025). "Our previous research demonstrated the proliferation and immune regulation of FGL1 in tumors, which indicated that FGL1 downregulation inhibits lung adenocarcinoma cell proliferation via MYC signaling." (PMID 41024301, 2025). "Our team previously demonstrated that FGL1 is tightly associated with the proliferation of PC9 and HCC827 lung adenocarcinoma cells by regulating the cell cycle through the MYC pathway." (PMID 36358792, 2022). "A previous study attempted to identify potential therapeutic target genes for HCC by using Gene Expression Omnibus (GEO) and The Cancer Genome Atlas (TCGA) databases, and FGL1 was identified as a possible biomarker in lung adenocarcinoma." (PMID 34069373, 2021). "FGL1 was suggested to be a biomarker for epithelial-mesenchymal transition and angiogenesis in specific lung adenocarcinomas." (PMID 34957095, 2021). "On the other hand, previous research has demonstrated that loss of FGL1 induces EMT (epithelial-mesenchymal transition) and angiogenesis in LKB1 mutant lung adenocarcinoma, creating a tumor microenvironment more suitable for tumor growth and development." (PMID 33832428, 2021). "However, few similar studies have been reported, and the role of FGL1 in other types of lung adenocarcinoma needs to be further studied and verified." (PMID 41024301, 2025). "Dual immunological and proliferative regulation of FGL1 was observed in lung adenocarcinoma (LUAD)." (PMID 38973608, 2024). "However, in the LKB1 mutant A549 lung adenocarcinoma cell line, the downregulation of FGL1 promotes the proliferation and epithelial–mesenchymal transition (EMT) of cancer cell." (PMID 36358792, 2022). "FGL1 has been suggested as a novel biomarker for angiogenesis in patients with lung adenocarcinoma." (PMID 34957095, 2021). "More interestingly, Bie and colleagues found that FGL1 affected the proliferation of lung adenocarcinoma cells by regulating the expression of vascular endothelial growth factor, hypoxia-inducible factor, insulin-like growth factor, and EGFR through functional experiments and RNA sequencing." (PMID 32778129, 2020). "Studies have shown that bone marrow stromal cells (BMSCs) overexpress FGL1 to repair acute liver injury by regulating p-STAT/STAT3, and overexpression of FGL-1 was associated with epithelial intermediate transformation and angiogenesis of LKB1-mutant lung adenocarcinoma cells." (PMID 32778129, 2020).
liver cancer (13 papers, 2013 to 2025). An epithelial or non-epithelial malignant neoplasm that arises from the liver. "By using mouse models of liver metastasis and orthotopic liver cancer, it was demonstrated that Fgl1 deficiency or anti-FGL1 mAb blockade restrained liver metastasis and tumor growth." (PMID 38973608, 2024). "FGL1 deficiency inhibited liver metastasis of CRC, indicating that a high level of FGL1 in the liver might be associated with liver cancer development and progression." (PMID 38973608, 2024). "Upregulation of FGL1 facilitates tumour progression and metastasis in liver cancer, non‐small‐cell lung cancer and esophageal squamous cell carcinoma." (PMID 39778025, 2025). "In humans, the downregulation of FGL1 is observed in 20% to 60% of liver cancer cases, and its expression correlated with the degree of tumor differentiation." (PMID 40832769, 2025). "This study reveals critical regulatory roles of FGL1 in the liver immune microenvironment and provides a new target of immune checkpoints for liver cancer immunotherapy." (PMID 38973608, 2024). "Some early studies suggest that FGL1 is down-regulated in human liver cancer tissues, inhibiting HCC development through various mechanisms." (PMID 38816776, 2024). "In this study, we further explored its critical role as a novel immune checkpoint in the progression of liver cancer since FGL1 is a hepatocyte-secreted protein." (PMID 38973608, 2024). "The possible reasons for the persistent low levels of FGL1 in the development of liver cancer have also been provided by some groups." (PMID 34975333, 2022). "FGL1 was found to be over‐expressed in human liver cancer as a major ligand of Lag‐3 which is responsible for its T‐cell inhibitory function, and had a link with a poor prognosis and therapeutic outcome." (PMID 32810392, 2020). "Similarly, in liver cancer, FGL1 expression decreases with disease progression, and compared with wild-type mice, the growth rate of liver cancer in FGL1-knockout mice is faster, possibly involving the AKT and mTOR pathways." (PMID 41024301, 2025). "To further investigate whether FGL1 in liver cancer tissues is correlated with patient outcomes, we performed IHC staining for FGL1 using the TMA from Cohort 2 patients (P< 0.001)." (PMID 36993960, 2023). "According to in vitro and in vivo experiments, FGL1 leads to TRM suppression in HCC, and blockade of the LAG3 and FGL1 pathways might restore the TRM-mediated anti-tumor response in liver cancer." (PMID 36993960, 2023). "HNF1α acts as an important liver-specific cis-acting element for FGL1, and downregulation of HNF1α might responsible for the inhibition of FGL1 transcription in liver cancer." (PMID 34975333, 2022). "We first explored whether Oxysophocarpine treatment could affect the expression of FGL1 in liver cancer cells." (PMID 32810392, 2020). "FGL1 inhibited CD8+ T and NK cell functions via its receptor LAG-3, explaining to some extent why the liver has high susceptibility to primary tumors and is a common site of tumor metastasis and providing a strategy of checkpoint targeting for liver cancer immunotherapy." (PMID 38973608, 2024). "The PDGF/PDGFRB signaling we observed in the low MC region activates the downstream lymphocyte-activation gene 3 (LAG3)/fibrinogen-like protein 1 (FGL1) immunosuppressive axis, adding complexity to liver cancer immune evasion analysis." (PMID 39015573, 2024). "Genetic ablation or antibody blockade of FGL1 signaling inhibited liver metastasis and tumor growth by promoting CD8+ T and NK cell functions, suggesting that FGL1 is an immunotherapy target for liver cancer." (PMID 38973608, 2024). "Thus, FGL1 may serve as an independent biomarker for the prognosis of patients with liver cancer." (PMID 36993960, 2023). "Whether FGL1, a new ligand of LAG-3, has therapeutic potential for liver cancer still needs to be investigated." (PMID 38973608, 2024).
liver cancer (continued). "FGL1 plays a crucial role in promoting hepatocyte growth, regulating lipid metabolism, and influencing the tumor microenvironment (TME), contributing significantly to liver repair, non-alcoholic fatty liver disease (NAFLD), and liver cancer." (PMID 38816776, 2024). "FGL1 is primarily associated with liver regeneration, non-alcoholic fatty liver disease (NAFLD), and liver cancer, while FGL2 is known to be involved in viral hepatitis, liver fibrosis, HCC, and liver transplantation." (PMID 38816776, 2024). "There was no significant change in the proliferation of liver cancer cell lines in the Fgl1-knockdown Hepa1-6 murine model compared with that in the sham group." (PMID 36993960, 2023). "FGL1/LAG3 blockade combined with natural products, seems to be more effective against liver cancer." (PMID 34975333, 2022). "As the expression of LAG3 is low in the liver, the FGL1/LAG3 interaction may not contribute to liver cancer." (PMID 40832769, 2025). "In conclusion, hepatocyte-derived FGL1 played critical immunoregulatory roles in the liver and contributed to liver metastasis and tumor growth by inhibiting CD8+ T and NK cell functions via the receptor LAG-3, providing a new strategy for liver cancer immunotherapy." (PMID 38973608, 2024). "FGL1 and LSECtin, both of which are overexpressed in healthy livers and downregulated in liver cancer patients according to The Cancer Genome Atlas, do not affect the long‐term survival of liver cancer patients." (PMID 35390227, 2022). "Thus, FGA, FGB, FGG and FGL1 could be important direct target genes of FOXA1 that are involved in EMT of lung and liver cancer specifically." (PMID 24093963, 2013). "Thus, FGL1 blockade in liver tissues primarily affects the tumor microenvironment through the immunological regulation of CD8+ T and NK cells, which is a unique feature of liver tissue and may become an important means of inhibiting liver cancer." (PMID 38973608, 2024). "Interestingly, expression of the newly identified ligand FGL1 has also been shown to be upregulated in cancer, and blockade of the FGL1-LAG-3 interaction stimulates immune responses and exhibits therapeutic effects on mouse tumor models (MC38 colon cancer and Hepa1-6 liver cancer)." (PMID 31681269, 2019).
Insulin resistance (12 papers, 2021 to 2025). Increased resistance towards insulin, that is, diminished effectiveness of insulin in reducing blood glucose levels. "Excess FGL1 also causes obesity-related insulin resistance in skeletal muscle through the EGFR/JNK mediated pathway." (PMID 34975333, 2022). "In brief, elevated FGL1 in the liver under external stimulation promotes DNA synthesis, inhibits ROS production, and causes insulin resistance, steatosis and inflammation." (PMID 34975333, 2022). "Additionally, FGL1 has been implicated in metabolic diseases, including promoting insulin resistance and liver lipid metabolism disorder." (PMID 38816776, 2024). "Daily injections of recombinant FGL1 (1 mg/kg) for a week were sufficient to ameliorate the steatosis and insulin resistance in mice fed a high‐fat (16 weeks) or MCD (3 weeks) diet." (PMID 40832769, 2025). "Changes in FGL1 levels in the liver not only lead to hepatic metabolic disorders, but also affect obesity-related insulin resistance in adipose tissues and skeletal muscles." (PMID 34975333, 2022). "Further experiments indicated that FGL1 regulates metabolism by increasing hepatic lipid accumulation and inducing insulin resistance." (PMID 34956878, 2021). "FGL1 expression can also be regulated in chronic medical diseases, such as hyperlipidemia, insulin resistance, and hyperglycemia crisis." (PMID 34526102, 2021). "Accordingly, FGL1 knockdown improved insulin resistance in both high-fat-diet-fed mouse and ob/ob mouse." (PMID 34957095, 2021). "Increased plasma FGL1 levels disrupt insulin signaling to induce insulin resistance and type 2 diabetes through an extracellular signal-regulated kinase 1/2-dependent pathway." (PMID 34957095, 2021). "Recently, plasma tests in these patients have found that FGL1 is upregulated when insulin resistance occurs." (PMID 34526102, 2021). "For example, FGL-1 plays an important role in insulin resistance and T2D by ERK1/2-dependentmechanisms, andFGL-1 up regulation could increase ERK1/2 activity, inhibit insulin signaling and lead to insulin resistance." (PMID 41341131, 2025). "Levels of FGL-1 are higher in overweight and obese subjects, and are positively correlated with BMI, waist circumference, degree of obesity, and insulin resistance, suggesting thatFGL-1 may link obesity, diabetes and NAFLD." (PMID 41341131, 2025). "Additionally, FGL1 appears to be an atypical biomarker for nonalcoholic fatty liver disease, type 2 diabetes and obesity, and is involved in regulation of adipogenesis, gluconeogenesis, and insulin resistance through diverse molecular mechanisms." (PMID 34975333, 2022). "Furthermore, peripheral FGL-1 levels in patients with type 2 diabetes mellitus (T2DM) are significantly increased compared with those in normal subjects, and the elevated FGL-1 is independently associated with fasting glucose levels, insulin resistance and impaired glucose tolerance." (PMID 38705920, 2024). "Fibrinogen-like protein 1 (FGL-1), a member of the fibrinogen family, is derived from hepatocytes, and plays crucial roles in hepatic steatosis and insulin resistance." (PMID 36556955, 2022). "This high level of FGL1 could act on C2C12 cells (myoblasts) and generate insulin resistance through the phosphorylated JNK pathway." (PMID 34526102, 2021). "Moreover, Palmitic acid has been shown to upregulate FGL1 expression in primary hepatocytes via C/EBP-β mediated transcriptional activation, leading to the phosphorylation of C-Jun N-terminal kinases (JNKs) and subsequent insulin resistance in skeletal muscle cells." (PMID 38816776, 2024).
melanoma (12 papers, 2021 to 2025). A malignant, usually aggressive tumor composed of atypical, neoplastic melanocytes. "FGL1 is upregulated in tumor tissues (including lung, prostate, melanoma, colorectal, breast, and brain tumors) based on meta-analysis of the Oncomine databases." (PMID 38139416, 2023). "Blocking the interaction between LAG-3 and FGL1 with a monoclonal antibody increases intertumoral T cell responses and leads to decreased tumor size in murine models of melanoma." (PMID 35885017, 2022). "Apart from its relatively high expression in the liver and pancreas, FGL1 is upregulated in tumor tissues (including lung, prostate, melanoma, colorectal, breast and brain tumors) based on several datasets." (PMID 34526102, 2021). "In addition, FGL1 is upregulated in various solid tumors such as lung, prostate, melanoma, colorectal, breast cancer, and brain tumors." (PMID 35885017, 2022). "In metastatic NSCLC and melanoma, characterized by higher plasma FGL1 levels, poor outcome is found following anti-PD-1 therapy, indicating that FGL1 may play a role in tumor immune resistance." (PMID 35111155, 2021). "Kaplan-Meier Plotter analysis revealed that lower FGL1 expression correlated with longer OS in patients undergoing anti-PD1 therapy, including those with bladder cancer, glioblastoma, and melanoma." (PMID 40469297, 2025). "Most importantly, FGL1 will be a potential biomarker for predicting the outcome of PD-1/PD-L1 blockade therapy, since high plasma FGL1 levels were reported to be significantly correlated with a worse therapeutic response to anti-PD-1/PD-L1 therapy in NSCLC and melanoma patients." (PMID 34526102, 2021). "Recently, small extracellular vesicles (sEVs) released by metastatic melanomas carrying PD‐L1 on their surface were reported to successfully suppress the function of CD8+ T cells, which provided us with a rationale for developing FGL1 and PD‐L1 dual‐targeting sEVs as an anti‐rejection therapy." (PMID 34738731, 2022).
colon cancer (8 papers, 2019 to 2025). "In MC38 colon cancer mouse models, the inhibition of FGL1 by anti-FGL1 mAb and the knockout of FGL1 in cancer cells result in a potent antitumor effect, and the proliferation of cancer cells is significantly inhibited." (PMID 36358792, 2022).
colorectal cancer (8 papers, 2019 to 2025). A primary or metastatic malignant neoplasm that affects the colon or rectum. "In the MC38 colorectal cancer model, ablation of FGL1-LAG-3 interaction with either anti-FGL1 or anti-LAG-3 blocking antibodies inhibits tumor growth." (PMID 30863404, 2019).
diabetes (8 papers, 2020 to 2025). "As a potential diagnostic biomarker and indicator of NAFLD, diabetes and obesity treatment response, FGL1 is a candidate target worthy of further study at the mechanistic level in the continual search for therapeutic remedies for these diseases." (PMID 34975333, 2022). "It seems that the association of upregulated circulating FGL1 with disease activity is beneficial for the inhibition of autoimmunity but enhances the risks of obesity, diabetes and cardiovascular events." (PMID 33123164, 2020). "However, elevated hepatic FGL1 under high fat conditions can cause lipid accumulation and inflammation, which in turn trigger the development of non-alcoholic fatty liver disease, diabetes, and obesity." (PMID 34975333, 2022). "Increased FGL1 level is therefore a risk factor for both diabetes and NAFLD." (PMID 33123164, 2020). "Mice and human studies show that FGL1 is indirectly related to the occurrence of obesity and diabetes." (PMID 36011329, 2022). "In addition, FGL1 has been found to be involved in obesity, lung fibrosis, preeclampsia, diabetes mellitus, non-alcoholic fatty liver disease, and hyperlipidemia." (PMID 37153794, 2023). "FGL-1 is a novel hepatokine mainly expressed in the liver under normal physiological conditions, but whose levels are increased by high fat conditions and lead to lipid accumulation and inflammation, which in turn trigger the development of NAFLD, diabetes, and obesity." (PMID 41341131, 2025).
Obesity (8 papers, 2020 to 2025). Accumulation of substantial excess body fat. "FGL1 also has a role in obesity and is considered a novel therapeutic target to combat this condition due to FGL1 effects on individuals at an elevated risk of being obese." (PMID 35682868, 2022). "miRBase analysis showed that identified FGL1 3′UTR mutations may affect miRNA binding sites previously reported as correlated with obesity, including those involved in the insulin signaling pathway, maturity-onset diabetes of the young, type II diabetes mellitus, and adipocytokine signaling pathway." (PMID 36011329, 2022). "In addition, levels of FGL-1 and body fat percentage are positively correlated, and suggesting that FGL-1 as therapeutic target in obesity." (PMID 41341131, 2025). "However, Fgl1‐deficient mice fed a standard rodent chow displayed increased body weight and mildly increased fasting hyperglycemia without any modification of food intake compared to wild type mice, suggesting that FGL1 could be involved in the onset of obesity." (PMID 40832769, 2025). "Recently, the relationship between FGL1 and obesity was confirmed in obese individuals." (PMID 34975333, 2022). "There is a positive correlation between FGL-1 and obesity markers, and FGL-1 levels are reduced by laparoscopic sleeve gastrectomy (LSG) for weight loss, supporting our findings that exercise reduces decrease in the FGL-1 levels and also decreases body weight and adiposity." (PMID 41341131, 2025). "In order to investigate the contribution of hepatocyte‐derived FGL1 in MASLD, 6–8 week‐old Fgl1LWT and Fgl1LKO male mice were fed a normal chow or a western diet for 16 weeks to induce obesity coupled with reduced glucose tolerance, hepatic steatosis, and inflammation." (PMID 40832769, 2025). "ERK1/2 is activated by FGL-1 to induce lipogenesis, and increased ERK1/2 phosphorylation stimulates C/EBPβ.FGL1 facilitates adipogenesisbyaERK1/2-C/EBPβ- dependent pathway, and targeting FGL-1 could be a novel therapeutic strategy in obesity and its related disorders." (PMID 41341131, 2025).
non-small cell lung carcinoma (7 papers, 2020 to 2025). A group of at least three distinct histological types of lung cancer, including non-small cell squamous cell carcinoma, adenocarcinoma, and large cell carcinoma. "High FGL1 level in the blood is significantly associated with poor prognosis in patients with non-small cell lung cancer (NSCLC) and melanoma who have been treated with anti-PD-1/PD-L1 antibodies." (PMID 38098892, 2023). "A previous study has shown that the suppression of FGL1 inhibits the expression of caspase 3 and PARP1, thereby enhancing the inhibitory and apoptosis-inducing activities of gefitinib in the non-small cell lung cancer (NSCLC) cell line PC9/GR." (PMID 35776395, 2022).